TWIST1 (twist family bHLH transcription factor 1)
Diseases named in the same sentence as TWIST1 in open-access papers (continued):
Sharing a sentence is not in itself a finding about the gene and the disease.
ovarian carcinoma (continued). "However, when used as a biomarker in conjunction Twist1, the absence of CBX7 in Twist1-positive ovarian cancer cells confers worse outcomes." (PMID 38037081, 2023). "To explore whether TWIST1 could regulate β-catenin, we uncovered the negative role of TWIST1 in the expression of β-catenin at the protein level during the process of ovarian cancer stem cell differentiation." (PMID 36123378, 2022). "Meanwhile, another EMT-TF, Twist1, was recently identified as inducing DDR2 expression and ovarian cancer metastasis, suggesting that morphological changes by EMT-TFs might be a driving force for DDR2 expression and ovarian cancer progression." (PMID 34065317, 2021). "Therefore, PI3K, Akt, HIF-1α, Twist1, and DDR2 may serve as effective targets to attenuate the invasion and metastasis of ovarian cancer cells." (PMID 34065317, 2021). "Since previous reports indicated that HK2-mediated ovarian cancer cell invasion is mediated through the FAK/ERK1/2 pathway, and FAK promotes EMT in cancer cells by upregulating Twist1 and Snail expression, we examined whether HK2 regulates EMT in EC cells in a FAK-dependent manner." (PMID 34174908, 2021). "Moreover, the inhibition of STAT3 activity and Twist1 transcription could suppress EMT and inhibit tumor progression and chemoresistance in ovarian cancer and renal cancer cells." (PMID 32872659, 2020). "Although BOTs are not entirely recognized as malignant tumors and are not seen as a necessary process of transformation into ovarian cancer, in this study, we found some biomarkers related to EMTs, such as IL6, AKT1, MAPK3, SRC, TWIST1, and TGFB1." (PMID 33921111, 2021). "The expression of both TWIST1 and E12 were induced by hypoxia/HIF-1, yet the lack of TWIST1 in EOC stem cells in the presence of hypoxia prevented EMT, which illuminates the essential role of TWIST1 in the regulation of ovarian cancer differentiation." (PMID 25238494, 2014). "Many of the other EMT-related transcription factors, such as SNAI2, TWIST1, and ZEB1 are often overexpressed in the MAF signature, but SNAI1 is not (and, at least in ovarian carcinoma in which we have methylation data, this is due to its differentially methylated status)." (PMID 21047417, 2010).
colorectal cancer (69 papers, 2011 to 2026). A primary or metastatic malignant neoplasm that affects the colon or rectum. "Studies have indicated a pronounced elevation of TWIST1 protein in tissues from UC and UC-associated colorectal cancer, with the expression intensity being greater in the latter." (PMID 38510272, 2024). "The EMT-inducing TFs, Snai1, Slug, and Twist1, were upregulated in colorectal cancer (CRC)-associated tECs, both in primary tumors and in hepatic metastases when compared to paired nEC samples from adjacent tissue." (PMID 39095583, 2024). "In this study, TWIST1 is highly correlated with UC, and previous research has also indicated a strong association between TWIST1 and UC-associated colorectal cancer." (PMID 38510272, 2024). "Note that we previously reported the PC1 signature predicted disease progression and recurrence in CRC whereas TWIST1 overexpression was reported to be associated with nodal invasion (regional metastasis) in primary colorectal cancer." (PMID 35272617, 2022). "Having found a significant increase in mitotic aberrations associated with Twist1 overexpression, we asked if Twist1 induces CIN in colorectal cancer cells." (PMID 32337580, 2020). "TWIST1 over-expression in colorectal cancer is associated with gender and with a poor prognosis factor, such as nodal invasion, but its impact on the clinical outcome of the disease is still not clear." (PMID 21464926, 2011). "Given that UC serves as a precancerous lesion for UC-associated colorectal cancer, our research provides valuable clues for investigating TWIST1 as a potential risk marker in the onset, development, and transformation of UC into UC-associated colorectal cancer." (PMID 38510272, 2024). "Interestingly, methylation of TWIST1 promoter is associated with protein expression in tumor stroma to influence the epithelial-mesenchymal transition-like tumor budding phenotype in colorectal cancer." (PMID 26023736, 2015). "Overexpression of Twist1 effectively counteracts the inhibitory effects of miR-489 on colorectal cancer (CRC) progression." (PMID 40612103, 2025). "Reversing epithelial–mesenchymal transition (EMT) represents another avenue: the small−molecule reversine inhibits Twist1 nuclear translocation, reestablishing 5-fluorouracil sensitivity in colorectal cancer cells by restoring epithelial characteristics." (PMID 41229498, 2025). "TPPP3 modulates STAT3/Twist1 signaling in non-small-cell lung carcinoma and colorectal cancer, promoting proliferation, migration and invasion." (PMID 41148789, 2025). "BEST4 relays the HES4 signal and downregulates TWIST1 expression to counteract epithelial-to-mesenchymal transition (EMT) induction in colorectal cancer (CRC)." (PMID 39699952, 2024). "Twist1 participates in chromosomal and genomic instability and downregulates critical cell cycle checkpoint factors in colorectal cancer cells." (PMID 38528462, 2024). "When TFF3 is overexpressed in colorectal cancer cells, transcription factors such Twist1, Snail, and Vimentin are expressed more often while E-cadherin levels are concurrently decreased." (PMID 39839775, 2024). "PEVs from colorectal cancer patients accelerate metastasis by increasing EMT markers TWIST1 and VIM in the colorectal cancer cell line, as well as enhancing COX2 and TxA2 generation to promote cancer development." (PMID 37374185, 2023). "The correlation between the mRNA levels of ZEB2 and TWIST1 was progressively stronger in colorectal cancers with moderate malignancy at G2 level and high malignancy at G3–G4 level, compared to those with low malignancy at G1 level." (PMID 35884488, 2022). "In colorectal cancer, up-regulation of LINC00467 reduces the expression of cyclin A1, cyclin D1, CDK2, CDK4 and Twist1, and enhances the expression of E-cadherin, thus promoting the development of colorectal cancer." (PMID 34888249, 2021). "We surmise that Twist1-mediated decrease in lamin levels is an indirect means of contributing to CIN in colorectal cancers." (PMID 32337580, 2020).
colorectal cancer (continued). "Taken together, this suggests that Twist1 overexpression induces and enhances DNA double strand breaks in colorectal cancer cells." (PMID 32337580, 2020). "This is consistent with a marked increase in Twist1 levels across cancers as well as in the aggressive colorectal cancers inferred from TCGA patient datasets." (PMID 32337580, 2020). "Colorectal cancers (COADREAD) also showed a high expression of Twist1, especially in the late stage tumors." (PMID 32337580, 2020). "In summary, Twist1 overexpression represses checkpoint genes at the transcriptional level, otherwise required for the maintenance of chromosomal stability of colorectal cancer cells." (PMID 32337580, 2020). "Remarkably, the levels of the Bub1 and BubR1 proteins of the SAC showed a significant and comparable decrease in both colorectal cancer cell lines upon Twist1 overexpression." (PMID 32337580, 2020). "Notwithstanding a striking downregulation of the checkpoint factors at the transcript and protein levels, CIN− (DLD1) or the CIN+ (SW480) colorectal cancer cells nevertheless resist an increase in their overall ploidy levels upon Twist1 overexpression." (PMID 32337580, 2020). "Here, we show that Twist1 overexpression induces EMT to varying extents in the two colorectal cancer cell lines." (PMID 32337580, 2020). "Taken together, our studies suggest an overarching role of Twist1 in modulating chromosomal stability in colorectal cancer cells." (PMID 32337580, 2020). "We therefore studied the effect of transiently overexpressing Twist1 in two independent colorectal cancer cell lines—(i) DLD1—a near diploid, mismatch repair-deficient cell line and (ii) SW480—aneuploid, mismatch repair proficient cell line." (PMID 32337580, 2020). "This is accompanied by an increase in whole chromosomal copy number gains and losses, underscoring the role of Twist1 in inducing chromosomal instability (CIN) in colorectal cancer cells." (PMID 32337580, 2020). "In summary, Twist1 overexpression shows a decrease in the levels of CIN regulators, which further underscores the contribution of Twist1 to CIN in colorectal cancer cells." (PMID 32337580, 2020). "We overexpressed Twist1 independently in the two colorectal cancer cell lines and performed immunoblotting on whole cell extracts derived from these cells." (PMID 32337580, 2020). "Here we overexpressed Twist1 and determined the frequency of nuclear blebs and micronuclei in colorectal cancer cells." (PMID 32337580, 2020). "Taken together, these studies highlight the mechanistic involvement of Twist1 in the deregulation of factors that maintain genome stability during EMT in colorectal cancer cells." (PMID 32337580, 2020). "Notwithstanding their genetic background, colorectal cancer cells nevertheless maintain their overall ploidy, while the downstream effects of Twist1 enhance CIN and DNA damage enriching for sub-populations of aggressive cancer cells." (PMID 32337580, 2020). "In summary, CIN is induced in a differential manner in the two colorectal cancer cell lines, upon Twist1 overexpression, since DLD1 cells exhibit both whole chromosomal gains and losses, while SW480 cells predominantly show whole chromosomal losses." (PMID 32337580, 2020). "TWIST1 is frequently reported to be highly expressed in colorectal cancer and is correlated with tumor formation and progression." (PMID 26820130, 2016). "A recent work by Laghi and colleagues investigated TWIST1 in cell lines and samples of colorectal cancer patients." (PMID 25528769, 2015). "TWIST1 expression has also been quantified in peripheral blood from patients with colorectal cancer and shown to correlate not only with disease progression but with stem cell marker CD133 expression." (PMID 25528769, 2015).
colorectal cancer (continued). "Our data show that SNAI1 and Twist1 are already expressed in benign precursor lesions of colorectal cancer and that SNAI1 expression was significantly correlated with lower expression of CDH1." (PMID 23029563, 2012). "We tested, by RT-PCR, the expression levels of TWIST1 in normal and tumor paired-sample tissues from a series of 151 colorectal cancer patients, in order to investigate its prognostic value as a tumor marker." (PMID 21464926, 2011). "The analysis of TWIST1 expression levels in tumor and normal matched tissues from 151 patients with colorectal cancer showed that the expression of TWIST1 is restricted to the tumor mass." (PMID 21464926, 2011). "Colorectal cancer is one of the tumors in which TWIST1 is over-expressed, but its involvement in the clinical outcome of the disease is still unclear." (PMID 21464926, 2011). "We examined the expression of TWIST1 in the normal and tumor tissues of a large series of 151 colorectal cancer patients." (PMID 21464926, 2011). "Furthermore, EMT transcription factors upregulate ABC transporter genes such as ABCB1 and ABCC1, increasing drug efflux; for example, Twist1 binds the ABCB1 promoter in colorectal cancer, driving irinotecan export and resistance." (PMID 41229498, 2025). "Thus, it is possible that ML-60218 indirectly affects TWIST1 by blocking NF-κB activity and altering the migratory potential of colorectal cancer cells." (PMID 36900285, 2023). "TWIST1/2-positive high-grade tumors exhibit both lymphatic vessel invasion and lymph node metastasis suggesting that TWIST promoter methylation may serve as a prognostic marker for patients with colorectal cancer." (PMID 33803458, 2021). "In addition, YTHDC2 exerts a promoting role in the colorectal cancer metastasis through the hypoxia/HIF-1α/Twist1 signaling pathway." (PMID 34497675, 2021). "Finally, DNA methylation has been also shown to regulate TWIST1/2 promoter methylation and correlate inversely with the TWIST1/2 expression levels in colorectal cancer." (PMID 33803458, 2021). "In addition, Prdx2 inhibited EMT in a colorectal cancer model, reducing invasive characteristics, via Twist1, Snail, ZEB1, and ZEB2." (PMID 33182509, 2020). "Here we show that Twist1 induces chromosomal and genomic instability in colorectal cancer cells." (PMID 32337580, 2020). "In summary, colorectal cancer cells exhibit EMT to varying extents upon Twist1 overexpression." (PMID 32337580, 2020). "Since chromosomal aberrations such as deletions are consequences of DSB formation, we sought to examine whether Twist1 overexpression induces DNA DSBs in colorectal cancer cells." (PMID 32337580, 2020). "The lncRNA TUG1 is required for TGF-β/TWIST1/EMT-mediated metastasis in colorectal cancer cells." (PMID 32669962, 2020). "Interestingly, promoter hypermethylation of TWIST1 was also observed in the development of colorectal cancer, vulvar cancer and tonsillar squamous cell carcinoma." (PMID 26683359, 2016). "In colorectal cancers, TWIST1 and TWIST2 expression was essentially restricted to stromal cells." (PMID 25528769, 2015). "Tumor budding in colorectal cancer is likened to an epithelial-mesenchymal transition (EMT) characterized predominantly by loss of E-cadherin and up-regulation of E-cadherin repressors like TWIST1 and TWIST2." (PMID 25528769, 2015). "Moreover, Ashktorab and colleagues, performing an extensive bioinformatics work on CpG island Methylator Phenotype, identified TWIST1 as markedly hypermethylated in colorectal cancer." (PMID 25528769, 2015). "In addition, MEOX2 promoter sequences were recently used as part of a test for cancer-specific DNA methylation cluster markers in colorectal cancer, and TWIST1 methylation was assessed at promoter sequences in lung AD patients." (PMID 25460568, 2014).
colorectal cancer (continued). "Since, according to this result, the expression levels of TWIST1 in human colorectal cancer could be considered a poor prognosis factor, we were interested in the clarification of its possible prognosis value at each different colorectal tumor stage." (PMID 21464926, 2011). "In this context, MA was shown to induce E-cadherin while reducing Snail, Slug, and Twist1/2 expression, preventing the nuclear translocation of β-catenin, leading to the restoration of tight and adherent junctions between epithelial cells in colorectal cancer cells." (PMID 39863145, 2025). "Thus, we detected the expression of MMP9, MMP12, and TWIST1 in colorectal cancer cells." (PMID 26820130, 2016). "Stromal cells may influence tumor budding in colorectal cancers through expression of TWIST1." (PMID 25528769, 2015). "miR‐15 also promoted the malignant phenotypes of colorectal cancer by increasing PTEN/AKT and STAT3/TWIST1 signaling pathways." (PMID 39901895, 2025). "In prostate cancer, colorectal cancer, and gastric cancer, CHRF influences Twist1 or other EMT-related factors through miR-489 or miR-10b, facilitating the EMT of cancer cells." (PMID 40612103, 2025). "In colorectal cancer, CRC, MFAP2 expression downstream of TWIST1 led not only to platinum resistance but also to a CSC phenotype." (PMID 38139368, 2023). "In colorectal cancer, FAP+CAF secretes TGFβ, which activates the classical TGFβ signaling pathway and induces transcriptional regulation of Snail1 and Twist1 target genes, leading to EMT in cancer cells." (PMID 37277751, 2023). "In colorectal cancer, increased AXL contributes to the upregulation of TWIST1, which is directly related to EMT and mediates resistance to PLK1 inhibitors." (PMID 37328828, 2023). "Oxaliplatin and 5-fluorouracil resistance in colorectal cancer (CRC) can also result from the upregulation of Akt signals in tandem with STAT3 and TWIST1 activation." (PMID 38139368, 2023). "In colorectal cancers, AXL induces the expression of Twist family BHLH transcription factor 1 (TWIST1) and mediates resistance to polo-like kinase 1 (PLK1) inhibitor." (PMID 37328828, 2023). "lncRNA TUG1 promoted the proliferation and migration of colorectal cancer cells through the miR-145-5p/TRPC6 pathway, EMT pathway, miR-26a-5p/MMP14/p38MAPK/Hsp27 axis, Twist1/EMT signal pathway, or by overexpression." (PMID 34039257, 2021). "The present study was aimed to investigate expressions of TWIST1 and CD105 in colorectal cancer (CRC) patients." (PMID 33752711, 2021). "Taken together, Twist1 overexpression induces and enhances levels of nuclear aberrations and CIN in colorectal cancer cells." (PMID 32337580, 2020). "Correlation analysis of Twist1 and CCL2 expression in cohort (n=83) colorectal cancer (CRC) tissues." (PMID 33330033, 2020). "Correlation analysis of FOXQ1 and Twist1, CCL2, or CD31 expression in cohort (n=83) colorectal cancer (CRC) tissues." (PMID 33330033, 2020). "Our studies unravel a positive correlation between Twist1 overexpression and CIN in colorectal cancer cells." (PMID 32337580, 2020). "Twist1-induced CIN is characterized by both losses and gains of chromosomes in the near diploid DLD1 (CIN-) colorectal cancer cells, while the aneuploid SW480 (CIN+) colorectal cancer cells show chromosomal losses." (PMID 32337580, 2020). "We evaluated TWIST1 and TWIST2 methylation status in six well-established colorectal cancer cell lines and their corresponding immunohistochemistry detection." (PMID 25528769, 2015). "We also included colorectal cancer EMT markers, TWIST1 and SNAI1." (PMID 34214079, 2021). "The results of this study suggest that TWIST1 and to a lesser degree TWIST2 expressed within the tumor stroma could contribute to the EMT-like tumor budding phenotype in colorectal cancers." (PMID 25528769, 2015). "Other groups have reported on TWIST1 and TWIST2 methylation in colorectal cancer." (PMID 25528769, 2015).